STAT3 (signal transducer and activator of transcription 3)
Diseases named in the same sentence as STAT3 in open-access papers (continued):
Sharing a sentence is not in itself a finding about the gene and the disease.
breast cancer (continued). "Our results in this study showed that betavulgarin inhibited the Stat3/Sox2 signaling pathway and induced BCSC death, indicating that betavulgarin might be a potential natural compound that targets breast cancer and BCSCs." (PMID 32630026, 2020). "Interestingly, the restoration of LIFR in highly aggressive MDA-MB-231 cells by treatment with a histone deacetylase inhibitor restores STAT3 signaling downstream of LIF:LIFR, which has been proposed to promote drug resistance by breast cancer cells." (PMID 32023849, 2020). "STAT3 is an oncogenic transcription factor that is downstream of Janus-activated kinase 2 (JAK2), a non-receptor tyrosine kinase commonly amplified and hyperactive in TNBC and HER2-enriched breast cancers." (PMID 32957513, 2020). "Our results also revealed that the GREM1-MMP13 signaling pathway was triggered by activation of STAT3, suggesting that the GREM1-STAT3-MMP13 axis might be a new therapeutic target for breast cancer metastasis." (PMID 33287358, 2020). "Therefore, it appears that STAT3 signaling is an important mediator of EMT and stemness across many genetically-distinct breast cancers." (PMID 32391382, 2020). "In accordance with our results, researches have demonstrated that CXCR2+ MDSCs were predominately expanded and recruited in breast cancer and could boost EMT of breast cancer cells dependently on IL-6/STAT3 signaling." (PMID 32092078, 2020). "Our results may bring insights to the HIF‐1α/STAT3 interaction in breast cancers and suggest sanguinarine may potentially be recognized as HIF‐1α/STAT3 targeted compound for disturbing the growth of human breast cancers." (PMID 32065498, 2020). "Furthermore, in 11 patients’ samples, the enrichment of STAT3/G9a was established at the miR-200c promoter in TNBC, which involves are more aggressive tumors in comparison with luminal breast cancer." (PMID 33334030, 2020). "In addition, STAT3 knockdown or JAG1 knockdown reduced the secretion and protein expression of IL-4 and IL-6 in breast cancer cells, it also inhibited the proliferation of breast cancer cells." (PMID 32943090, 2020). "The leptin/ObR axis through the activation of JAK2/STAT3, MEK, and PI3K/Akt signalings intimately controls different cellular activities, including mitogenesis, survival, transformation, migration, and invasion of breast cancer cells." (PMID 32260113, 2020). "While OSM, LIF, and IL-6 can induce STAT3, AKT, and ERK signaling in breast cancer cells, in the absence of studies using combinations of STAT3, AKT, and ERK inhibitors, it is difficult to determine which is the dominant downstream mediator." (PMID 32023849, 2020). "While it may be tempting to speculate on the role of STAT3 in LGR5 expression in mammary stem cells and breast cancer stem cell development given the interplay between NFKB and STAT3 signalling, this however requires further experimental evidence." (PMID 32331320, 2020). "Activated STAT3 increases RANTES (regulated upon activation, normal T cell expressed and secreted factor) and anti-apoptotic Bcl-2 and Bcl-xL expression levels that contributes to tamoxifen-resistance in breast cancer." (PMID 32872659, 2020). "In addition, HNK-mediated STAT3 inactivation triggered the STAT3-mediated release of ZEB1 from the E-cadherin promoter, increasing E-cadherin expression and inhibiting EMT of breast cancer cells accordingly." (PMID 32014049, 2020). "STAT3 signaling pathway plays a crucial role in proliferation (Bcl-2, Survivin), angiogenesis (HIF1α, VEGF), and epithelial-mesenchymal transition (Vimentin, MMP-9) in breast cancer cells and has been validated as a drug target for cancer therapy." (PMID 31948057, 2020). "Several signaling pathways have been demonstrated to enhance proliferative of breast cancer cells, including the activation of JAK/STAT3 and PI3K/Akt by leptin, as well as JAK2 activation-mediated human epidermal growth factor receptor-2 (HER2) transactivation." (PMID 33123472, 2020).
breast cancer (continued). "Our results in this study show that tangeretin inhibits the Stat3 signaling pathway and induces CSC death, indicating that tangeretin may be a potential natural compound that targets breast cancer cells and CSCs." (PMID 32503228, 2020). "Stat3 oncogene downstream of JAK modulates transcriptional activation and repression of survivin in lymphoma, while the protein directly binds to survivin promotor and inhibit apoptosis in breast cancer cells." (PMID 32691369, 2020). "CYM-5478 treatment, however, rescued phospho-Stat3 protein expression only in the neural cell line and not in the breast cancer cell line." (PMID 31952197, 2020). "It was reported that SOCS6 could decrease the protein levels of p-STAT3 and HIF-1α in breast cancer and hepatocellular cancer." (PMID 32519748, 2020). "IDO was upregulated in breast cancer-derived MDSCs via IL-6-triggered STAT-3 activation, which activated the non-canonical NFκB pathway resulting in enhanced transcriptional activity of the IDO promoter." (PMID 33072086, 2020). "In breast cancer, tumors, and cell lines, CSE favors cell proliferation and migration under the command of STAT3, a member of JAK/STAT pathway; while in a murine model, CSE is stated as controlling the metastatic behavior of breast cancer cells through VEGF-dependent PI3K and MAPK pathways." (PMID 32714858, 2020). "Moreover, STAT3 can be activated by other stimulators such as EGF and VEGF, which are important in formation of stromal compartment in breast cancer." (PMID 32649314, 2020). "Based on the results of this study, miR-93-5p blocks both STAT3 and megakaryoblastic leukemia/myocardin-like 1 (MLK-1) as important regulators of cellular metabolism to suppress EMT resulting in reduced migration of breast cancer cells." (PMID 32612456, 2020). "Consistent with that, some studies previously reported that M2 macrophage secreted IL-8 via the STAT3/MALAT1 pathway to promote prostate tumorigenesis, and ERK/STAT3 axis could drive breast cancer progressions by stimulating M2 macrophage." (PMID 32486001, 2020). "Accordantly, targeting G-CSF/Stat3 signaling with G-CSF-neutralizing antibody, a chemical inhibitor, or siRNAs for Stat3 could all abrogate CAA- or G-CSF-induced migration and invasion of breast cancer cells." (PMID 32242230, 2020). "We initially investigated the correlation between STAT3 and IKKα, particularly in the context of the non-canonical NF-κB pathway, using specimens from patients with breast carcinoma." (PMID 33396715, 2020). "With regard to uncovering the novel therapeutic targets and/or strategies to treat breast carcinomas, it would be worthwhile to understand how STAT3 interacts with the non-canonical NF-κB pathway." (PMID 33396715, 2020). "This STAT3-dependent IKKα stabilization can further escalate tumorigenesis in human breast carcinoma through the non-canonical activation of NF-κB." (PMID 33396715, 2020). "We have previously reported that inhibition of STAT3 can induce apoptosis in H-Ras transformed human breast epithelial (H-Ras MCF-10A) cells, which corroborates the crucial role of STAT3 in the progression of human breast carcinoma." (PMID 33396715, 2020). "Their study showed that IL8 secretion from breast cancer cells following PI3K/mTOR inhibition consistently enhanced JAK2/STAT5 phosphorylation but not STAT3 phosphorylation." (PMID 31324052, 2019). "Co-culture of macrophages with breast cancer cells induces sustained release of TNF-α and IL-6 from both cell types, resulting in activation of NF-κB, STAT3, and ERK-1 and hyperphosphorylation of ERα (rendering it constitutively active) in the breast cancer cells." (PMID 30736340, 2019). "Thus, the inhibition of the coactivation function of STAT3 resulted in the suppression of expression of pluripotency factors in MCF7, MDA-MB-231, SUM149, and SUM159 breast cancer cells." (PMID 31877856, 2019).
breast cancer (continued). "The reduced expression levels of anti-apoptotic proteins, Bcl2 and Stat3, plus cell cycle regulator protein, Cyclin D1, using Real-Time PCR confirm that the C-PC-induced death of MCF-7 human breast cancer cells occurred through the mitochondrial pathway of apoptosis." (PMID 31263160, 2019). "In this study, we found that STAT3 could also mediate IL-6-induced MMP2 and MMP9 expression and breast cancer cell migration." (PMID 31409371, 2019). "Moreover, in high-IL-6-secreting MDA-MB-231 breast cancer cells, HIC1 was restored upon knocking down IL-6 expression, accompanied by decreased STAT3 activity." (PMID 31795965, 2019). "In this study, a STAT3 ChIP-seq peak file and a DGE file upon STAT3 knock-down in a breast cancer cell line were used to evaluate whether the use of ensemble mode can improve the performance of Cistrome-GO." (PMID 31053864, 2019). "Our data are in line with the work of Yeh and colleagues demonstrating a role for intracellular, but not extracellular progranulin, in sustaining STAT3 tyrosine phosphorylation and oncogenic activity in breast cancer cells." (PMID 31361391, 2019). "Our research group showed that HNK inhibits growth of breast cancer cells by inducing AMP-activated protein kinase in a LKB1-dependent manner and inhibits epithelial-mesenchymal transition and stemness by modulating Stat3/Zeb1/E-Cadherin axis." (PMID 31618928, 2019). "This elevated STAT5 activity trends with more differentiated and lower grade tumors, suggesting that STAT5 does not induce the aggressive cancer cell program initiated by STAT3, at least in breast cancer." (PMID 31684144, 2019). "Next, we examined whether AICAR-induced AMPK activation could mimic MTF reduction of IL-6-induced phosphorylation of STAT3 and NF-κB in MBCDF and MBCD17 breast cancer cells." (PMID 31337349, 2019). "Indeed, they showed that the functional cooperation of the Stat3 and AP-1 transcription factors is required for the transcription of MMP-9 gene in breast cancer cells." (PMID 31456939, 2019). "And MiR-93-5p inhibited the EMT of breast cancer cells via targeting MKL-1 and STAT3." (PMID 31409371, 2019). "PAK1/Stat3 signaling regulates CSC formation, and PAK1 may be an important target for treating breast cancer." (PMID 31658701, 2019). "In addition, the binding of vascular endothelial growth factor (VEGF) to its receptor 2 (VEGFR2) induces STAT3 phosphorylation and promotes the binding of STAT3 to the SOX2 and MYC promoter regions for their transcriptional activation in breast cancer cells." (PMID 31324052, 2019). "Considering the studies on the relationship between STAT3/p-STAT3 and survival prognosis of breast cancer patients are rare, and the papers did not use a uniformed statistical method, it’s very difficult to generate statistical graphs." (PMID 31375715, 2019). "On the other hand, cucurbitacin E induces cell arrest and apoptosis via STAT3 inhibition in human breast cancer Bcap-37 and MDA-MB-231 cells, and cucurbitacin I can inhibit STAT3 pathway to suppress cancer stem cell properties in anaplastic thyroid cancer ATC–CD133+ cells." (PMID 31719837, 2019). "STAT3 can be phosphorylated by activated JAK2 induced by IL-6, which is a key mediator of the inflammatory response and functions as a crucial regulator in the progression of breast cancer." (PMID 31186039, 2019). "MCT-1 stimulated IL-6/Stat3 signaling, suggesting that MCT-1 may also stimulate the NO/NOTCH pathway to mediate breast cancer metastasis and recurrence." (PMID 30885232, 2019). "In addition, SDF-1α binds to CXCR7, another chemokine receptor that is highly expressed on breast cancer cells, and enhances CXCR7-mediated tumor migration and metastasis by activating STAT3, MMP9, MMP2 and VCAM-1." (PMID 31219799, 2019). "The Stat3/PAK1 complex is essential for IL-6 gene expression and breast cancer stemness." (PMID 31658701, 2019).
breast cancer (continued). "Moreover, STAT3 has been proven to mediate the EGF-stimulating growth and survival effects of human breast cancer cells in vitro and, possibly, in vivo." (PMID 31485222, 2019). "The STAT3 SH2 domain binder inhibitor C188-9 inhibitor is currently tested in an ongoing phase I trial (NCT03195699) in patients with advanced-stage cancers, including breast cancer." (PMID 31581535, 2019). "ChIP-PCR products were detected in breast cancer cells by using a Stat3 or PAK1 antibody, but not detected with the control IgG." (PMID 31658701, 2019). "The immunofluorescence analysis with anti-PAK1 and anti-Stat3 in breast cancer cells with/without ivermectin treatment showed that colocalization of PAK1 and Stat3 in the nucleus was reduced by ivermectin treatment." (PMID 31658701, 2019). "We then assessed the functional relevance of combined STAT3 and SP1 activity in breast cancer." (PMID 30654518, 2019). "Whereas JAK/STAT3 signaling regulates lipid metabolism to promote FAO in BCSCs, which maintains the stemness and chemotherapy resistance of breast cancer cells, inhibiting FAO sensitizes breast cancer cells to chemotherapy." (PMID 31410189, 2019). "We demonstrated that carnosol exerts its effect against breast cancer, at least partly, through downregulation of the activity and the expression of MMP-9, inhibition of STAT3 signaling pathway through a ROS-dependent proteasome degradation of STAT3 protein." (PMID 31456939, 2019). "Furthermore, breast cancer cells cocultured with adipocytes or treated with either IL-6 or leptin displayed increased PLOD2 expression and activated JAK/STAT3 and AKT signaling pathways." (PMID 30563531, 2018). "In addition, miR-93-5p inhibits EMT of breast cancer cells via targeting megakaryoblastic leukemia (translocation) 1 (MKL-1) and STAT3." (PMID 29760585, 2018). "An influence of Notch signaling on STAT3 was observed in the absence of infection in breast cancer cells with hyperactivated Notch signaling." (PMID 30042932, 2018). "In addition, the HER2-STAT3 network has been shown to contribute to the aggressive phenotype of breast cancer stem cells, and the JAK2/STAT3 signaling pathway is required for the growth of CD44+CD24− stem cell-like breast cancer cells in human tumors." (PMID 29636641, 2018). "STAT3 and STAT5 may be activated in tandem in breast cancer, with 29% of tumours exhibiting this characteristic." (PMID 29875329, 2018). "However, it is still unclear how the STAT3 pathway regulates the growth of CD44+/CD24– and ALDH1 positive breast cancer cells in TNBC tumor models." (PMID 30542507, 2018). "Overall, high levels of STAT3 gene expression result in low survival in ovarian, lung, blood, and brain cancer, however, which is not clear in breast cancer." (PMID 29423040, 2018). "STAT3 also mediates oncogenesis by recruiting DNA methyltransferase 1 (DNMT1) to gene promoters to silence tumor suppressor genes, such as PTPN6, IL-2Rγ, CDKN2A, DLEC1, and STAT1 by CpG methylation in malignant T lymphocytes and breast cancer cells." (PMID 29728695, 2018). "Using the comprehensive survival analysis platforms Kaplan-Meier plotter, Oncomine, and PrognoScan, we have demonstrated the oncogenic role of STAT3 in ovarian, lung, blood, and brain cancer, however, which is not clear in breast cancer." (PMID 29423040, 2018). "TRIM14 overexpression increased the phosphorylation of STAT3 in breast cancer cells, while it was unclear whether TRIM14 was related to the STAT3 signaling during CRC progression." (PMID 30555277, 2018). "STAT3 activation was observed also in HER2 negative breast cancer, where activation of STAT3 also correlates with CSC properties." (PMID 29588647, 2018). "Due to the multifaceted roles of STAT3 and opposing roles between this protein and STAT1 along with previous reports that C12-HSL can downmodulate STAT3 in breast carcinoma cells, we investigated the effect of C12-HSL on changes in both gene and protein expression of these molecules in PCa cells." (PMID 29854771, 2018).
breast cancer (continued). "As expected, we observed that TNF-α could activate STAT3 via NF-κB and/or p38 signaling, leading to the up-regulation of HBXIP in breast cancer cells." (PMID 28938560, 2017). "In addition to its effect on constitutive TLR3, Wnt5a levels and subsequent IL-6 production and STAT3 levels/activation, we then evaluated the ability of C10 to inhibit the migration and viability/growth of MCF-7 breast cancer cells." (PMID 29371911, 2017). "Moreover, down-regulation of JAK1/STAT3 phosphorylation confirms that these factors are critically involved in LDR-attenuated EMT and stemness in breast cancer cells." (PMID 28240233, 2017). "We therefore investigated whether the positive influence of PTPRD on breast cancer cell stemness and EMT depends on IL-6/STAT3 signaling." (PMID 29228728, 2017). "In addition, our observation of TFF3-mediated activation of cSRC, STAT3 and p65 (subunit of NFκB) in HER2+/ER+ breast cancer cells is consistent with published literature." (PMID 29088778, 2017). "Indeed, tyrosine kinase inhibitors will impair both Y239/240 and Y313-ShcA phosphorylation to limit STAT3 immunosuppressive signals and activate STAT1 in breast cancer cells." (PMID 28276425, 2017). "Thus, by altering the phosphorylation status of STAT3, Dov targets the STAT3/LIN28/Let‐7/HMGA2 axis, which is emerging as an important oncogenic pathway for HMGA2 regulation in a subset of GB and breast cancer cells." (PMID 28500786, 2017). "Some results demonstrated that in MDA-MB-231 breast cancer cells (a TNBC cell line), Leptin induced breast cancer cell proliferation by ERK1/2 and STAT3 phosphorylation, and can function on regulation of tumor-stromal interactions to enhance the breast cancer stem cell activity." (PMID 27926517, 2017). "Moreover, silencing PRDM14 reduced the expression of CD44, which imparts cancer stemness, and STAT3, which is required for growth of CD44+CD24– stem cell-like breast cancer cells." (PMID 28423353, 2017). "We found about 75% inverse correlation between FRK and pSTAT3 in the 14 breast cancer cell lines tested, which aligns with our hypothesis that FRK is a negative regulator of STAT3 signaling." (PMID 29348886, 2017). "It was showed that Stat3 binds to its response elements at the HER2(ErbB-2) promoter to upregulate HER2(ErbB-2) transcription in breast cancer, highlighting Stat3 general role as upstream regulator of HER2(ErbB-2) expression in breast cancer." (PMID 28881721, 2017). "Furthermore, BENDA suppressed the function of cellular STAT3 as a transcriptional activator in a human breast cancer cell line, MDA-MB-468, with constitutively activated STAT3." (PMID 28125678, 2017). "Breast cancer cells that constitutively expressed Twist, a EMT regulator and direct transcriptional repressor of E-cadherin, exhibited aberrant IL-6 production and STAT3 activation." (PMID 28186964, 2017). "In addition, our previous study has shown that TFF3 promotes STAT3-dependent transcription of IL8, thereby stimulating angiogenesis in mammary carcinoma through the IL-8/CXCR2 axis." (PMID 29100386, 2017). "Consistent with our findings, expression of dominant-negative Stat3 or treatment with a JAK2/Stat3 inhibitor in breast cancer cell lines inhibited cell growth." (PMID 27589562, 2016). "Moreover, inflammatory cytokines, such as interleukin (IL)-6, induce LCN2 expression depending on activation of the STAT3 signaling pathway, IL-1β and the tumor cell-derived factor IL-10 also promote LCN2 expression in lung and breast cancer." (PMID 27912767, 2016). "Interestingly, we find that STAT3 is responsible, at least in part, for the transcriptional upregulation of PML in breast cancer." (PMID 27553708, 2016). "In this study, we found that long-term treatment of lapatinib in HER2-positive breast cancer cells led to increased IL6 expression, subsequent activation of downstream STAT3 signaling, and the maintenance of stemness, all of which contributed to acquired lapatinib resistance." (PMID 27694691, 2016).